WWOX (WW domain containing oxidoreductase)
Diseases named in the same sentence as WWOX in open-access papers (continued):
Sharing a sentence is not in itself a finding about the gene and the disease.
esophageal adenocarcinoma (2 papers, 2014 to 2020). A malignant tumor with glandular differentiation arising predominantly from Barrett mucosa in the lower third of the esophagus. "FHIT, WWOX span fragile sites (FRA3B and FRA16D) that are frequently mutated in precursor lesions to EAC, including Barrett's esophagus and Barrett's associated dysplasia." (PMID 24454681, 2014).
lung adenocarcinoma (2 papers, 2020 to 2021). A carcinoma that arises from the lung and is characterized by the presence of malignant glandular epithelial cells. "In patients with EGFR-L858R mutant lung adenocarcinoma, WWOX rs3764340 C/G polymorphism is also associated with tumor growth and invasion." (PMID 34948746, 2021). "In addition, WWOX rs3764340 and rs73569323 polymorphisms are highly correlated with the size of the primary tumor and the invasion of adjacent tissues in Taiwanese lung adenocarcinoma patients carrying the EGFR-L858R mutation gene." (PMID 34948746, 2021). "Moreover, it is necessary to study whether these polymorphic changes alter the function of WWOX protein in EGFR-mutated lung adenocarcinoma patients, especially L858R-mutated lung adenocarcinoma patients." (PMID 34948746, 2021). "Our data demonstrated that WWOX rs73569323 polymorphism is positively associated with tumor size and invasion in patients with EGFR-L858R mutant lung adenocarcinoma." (PMID 34948746, 2021). "Here, we found that WWOX SNPs exhibited significant associations with the size of the primary tumor and the invasion of adjacent tissues in patients with EGFR mutant lung adenocarcinoma, especially those with EGFR-L858R mutant." (PMID 34948746, 2021). "In Taiwanese patients with EGFR-mutant lung adenocarcinoma, especially those with EGFR-L858R gene mutation, the underlying mechanism of the WWOX signaling cascade dysregulation is worthy of further exploration." (PMID 34948746, 2021). "The data demonstrated that lung adenocarcinoma patients with EGFR L858R mutation, accompanied by WWOX rs73569323 C > T polymorphism, may show large tumor size and invasion of adjacent tissues." (PMID 34948746, 2021). "Our data suggest that WWOX SNPs may help to predict tumor growth and invasion in patients with EGFR mutant lung adenocarcinoma, especially those with the EGFR-L858R mutant." (PMID 34948746, 2021).
neuropathy (2 papers, 2016 to 2018). A disorder affecting the nervous system that manifests with pain, tingling, numbness, and/or muscle weakness. "The pleotropic roles of WWOX was not only restricted to tumor suppression, but also expanded to neuropathy as well as metabolic diseases." (PMID 26910372, 2016). "Indeed, data obtained from several animal models including flies, fish, and rodents demonstrate WWOX in vivo requirement and that its deregulation results in severe pathological consequences including growth retardation, post–natal lethality, neuropathy, metabolic disorders, and tumorigenesis." (PMID 30370248, 2018).
ovarian tumor (2 papers, 2011 to 2018). "Finally, WW domain containing oxidoreductase (WWOX) gene has been identified as a tumour suppressor gene and its expression has been shown to be reduced or absent in ovarian tumours." (PMID 29966369, 2018).
small cell lung carcinoma (2 papers, 2010 to 2021). Small cell lung cancer (SCLC) is a highly aggressive malignant neoplasm, accounting for 10-15% of lung cancer cases, characterized byrapid growth, and early metastasis. "Therefore, WWOX activation and block of JNK function could have similar effects to exert cell death and could bring up new strategies in specific cancers such as small cell lung cancer." (PMID 22615609, 2010).
thyroid tumor (2 papers, 2022 to 2026). A benign or malignant neoplasm affecting the thyroid gland. "The expression of WWOX protein was significantly lower in advanced thyroid tumors (T3/T4)." (PMID 41124647, 2026).
autosomal recessive spinocerebellar ataxia (1 paper, 2019). "In 2014, homozygous missense pathogenic variants in WWOX were identified by ES in six patients from twoconsanguineous families with autosomal recessive spinocerebellar ataxia(SCAR12)." (PMID 30356099, 2019).
B-cell neoplasm (1 paper, 2019). A group of heterogeneous lymphoid tumors generally expressing one or more B-cell antigens or representing malignant transformations of B-lymphocytes. "In order to better understand the role of WWOX in B cell neoplasms we targeted deletion of this gene early in B-cell development by crossing Wwoxflox/flox mice to Cd19Cre transgenic mice." (PMID 31275852, 2019).
bladder tumor (1 paper, 2014). "The aim of the present study was to determine the roles of the WWOX tumor suppressor and cancer-related genes in bladder tumor carcinogenesis." (PMID 25295115, 2014).
brain injuries (1 paper, 2017). "HA protects neurons from traumatic brain injuries, and this could be related with HA-mediated disappearance of Hyal-2, which reduces the WWOX/Smad4 signaling." (PMID 27845895, 2017).
brain tumours (1 paper, 2025). "In these brain tumours, loss of WWOX expression removes repression of pro-invasive genes such as MMP1, thereby facilitating HIF1A-driven ECM remodelling, which exacerbates tumour aggressiveness and further undermines genomic stability." (PMID 41007296, 2025). "Additionally, we observed the influence of the WWOX/HIF1A axis in brain tumours." (PMID 41007296, 2025). "We also showed that high WWOX/HIF1A ratios promote apoptosis and metabolic stability while suppressing EMT in brain tumours (GBM/LGG)." (PMID 41007296, 2025).
coronary artery disease (1 paper, 2022). "The associations among the EH domain-binding protein 1 (EHBP1), tubulin beta class I (TUBB), and WW domain-containing oxidoreductase (WWOX) single nucleotide polymorphisms (SNPs) and coronary artery disease (CAD) and ischemic stroke (IS) are not yet understood." (PMID 35559044, 2022).
COVID-19 (1 paper, 2025). A disease caused by infection with severe acute respiratory syndrome coronavirus 2. "GWAS identified candidate genes common to both COVID-19 severity and PASC, including CNTNAP2, WWOX, and ADAMTS17, which are implicated in extracellular matrix remodeling and neurological and cognitive development." (PMID 41561974, 2025).
Dysarthria (1 paper, 2023). Dysarthric speech is a general description referring to a neurological speech disorder characterized by poor articulation. "Learning disorders, dysarthria, nystagmus, and decreased reflexes in the upper and lower limbs have also been reported in patients with SCAR12 who presented a partial loss of function of WWOX protein." (PMID 38161429, 2023).
early-onset epilepsy (1 paper, 2021). "Here we presented an updated review of the literature describing the WWOX gene in early-onset epilepsy and associated neurological disorders." (PMID 33916893, 2021).
endometrial adenocarcinoma (1 paper, 2022). "Among numerous cellular processes that WWOX plays important role in, there are also reports associating it with EMT in the breast and endometrial adenocarcinoma." (PMID 35290621, 2022).
endometrial carcinoma (1 paper, 2021). A malignant tumor arising from the epithelium that lines the cavity of the uterine body. "The example of endometrial carcinoma revealed that integrin β4 and α2 are upregulated after WWOX silencing, suggesting that WWOX may regulate adhesion to laminin and collagens, respectively." (PMID 34204827, 2021).
Ewing sarcoma (1 paper, 2025). A small round cell tumor that lacks morphologic, immunohistochemical, and electron microscopic evidence of neuroectodermal differentiation. "Future large-scale, multi-institutional studies are warranted to validate RUNX2 as a prognostic marker, clarify the modulatory role of WWOX, and explore whether targeting this pathway can improve clinical outcomes in patients with Ewing sarcoma." (PMID 41141138, 2025). "A strength of this study is that it is among the first to simultaneously profile WWOX and RUNX2 in Ewing sarcoma, integrating molecular data with survival outcomes." (PMID 41141138, 2025). "The analysis involves a comparison of the median (min–max) expression levels of WWOX and RUNX2 in Ewing sarcoma cases (n=7) versus controls (n=5), based on tissue protein levels assessed via immunohistochemistry." (PMID 41141138, 2025).
Fanconi anaemia (1 paper, 2021). "Among these, there were FHIT, WWOX, FANCC (belonging to the Fanconi anaemia pathway), CADM1, and IMMP2L." (PMID 34187875, 2021).
folate deficiency (1 paper, 2019). A nutritional condition produced by a deficiency of FOLIC ACID in the diet. "Consistent with the induction of breakage at fragile sites (FS) upon folate deficiency, 24% of these alterations affected common FS, including the most active common FS genes FHIT, PARK2, and WWOX in the human genome." (PMID 30836646, 2019).
Hyperglycemia (1 paper, 2022). An increased concentration of glucose in the blood. "Additionally, hypoxia (normoglycemia and hyperglycemia) condition decreased WWOX protein expression in cytoplasm relative to normoxia (normoglycemia and hyperglycemia) in 1BR.3.N CONTR variant." (PMID 35328751, 2022). "WWOX overexpression resulted in a significant (p < 0.05) increase of the glucose uptake in normoxia hyperglycemia, however, when fibroblasts were cultured in hypoxia, the effect of WWOX overexpression was inverted, resulting in the reduction of glucose uptake." (PMID 35328751, 2022). "In normoxia hyperglycemia, hypoxia normo- and hyperglycemia, WWOX protein is significantly lower also in nucleus (all p < 0.05)." (PMID 35328751, 2022). "The immunocytochemistry confirmed downregulation of WWOX by transfection in normoxia normoglycemia (p < 0.001) and this effect was maintained in normoxia hyperglycemia (p < 0.001) and hypoxia normoglycemia (p < 0.01)." (PMID 35328751, 2022). "In normoxia hyperglycemia, in the case of WWOX overexpression, the PDHA gene expression increased 3-times (p < 0.05) compared to the appropriate control." (PMID 35328751, 2022). "WWOX downregulation resulted in HIF1α increase in normoxia normoglycemia and hyperglycemia condition (both p < 0.01)." (PMID 35328751, 2022). "We showed that HIF1A expression, its protein’s localization and transactivation function didn’t change in response to hyperglycemia in the control normal cell line, despite the reduction of WWOX protein." (PMID 35328751, 2022). "Hypoxia hyperglycemia was characterized by upregulation of some tested genes’ expression levels after WWOX downregulation." (PMID 35328751, 2022). "Furthermore, in normoxia hyperglycemia, our results showed that WWOX over-expression stabilizes high HIF1α protein amount without changes in its mRNA expression and protein localization." (PMID 35328751, 2022). "Moreover, in the 1BR.3.N WWOX KO cell line we recognized the increase of HIF1α transactivation function in hypoxia hyperglycemia condition." (PMID 35328751, 2022). "WWOX overexpression induced downregulation lactate dehydrogenase activity (p < 0.01) in hypoxia hyperglycemia and pyruvate dehydrogenase activity (p < 0.001) decrease in hypoxia normo- and hyperglycemia." (PMID 35328751, 2022). "The response of WWOX KO cells and tissues, including skin fibroblasts, to conditions of hyperglycemia, and hyperglycemia in conjunction with hypoxia is unknown." (PMID 35328751, 2022). "Lactate concentration were significantly higher in case of WWOX overexpression in comparison to 1BR.3.N WT cell line in normoxia normoglycemia and hypoxia hyperglycemia." (PMID 35328751, 2022). "We observed that WWOX silencing significantly increased glucose uptake in normoxia normoglycemia and reduced glucose uptake in hypoxia hyperglycemia conditions in the absence of insulin." (PMID 35328751, 2022). "What is more critical, in our observations of WWOX KO fibroblasts in comparison to control in normoxia hyperglycemia, we stated that the SLC2A1 and SLC2A4 mRNA increase does not translate into protein level and glucose uptake growth." (PMID 35328751, 2022).
hypospadias (1 paper, 2026). Hypospadias is the displacement of the urethral meatus on the ventrum of the penis. "This study aimed to investigate the WWOX gene in a patient presenting with hypospadias." (PMID 42082822, 2026).
Hypsarrhythmia (1 paper, 2022). Hypsarrhythmia is abnormal interictal high amplitude waves and a background of irregular spikes. "Vitamin B6 allowed patients with ALDH7A1 and PNPO mutations to achieve seizure-free status, oxcarbazepine was effective for patients with SCN2A, ATP7A, WWOX, and PRRT2 mutations, and ACTH was partly effective for DOCK6 mutation patients with spasms and hypsarrhythmia." (PMID 35715422, 2022).
injury (1 paper, 2017). Damage inflicted on the body as the direct or indirect result of an external force, with or without disruption of structural continuity. "Functional significance of the Hyal-2/WWOX signaling was tested in a traumatic brain injury model in rat, and the signaling revealed a critical role of nuclear Hyal-2 and WWOX in causing apoptosis under stress conditions." (PMID 27845895, 2017).
insomnia (1 paper, 2024). A sleep disorder characterized by difficulty in falling asleep and/or remaining asleep. "In the realm of sleep and circadian health, reported genetic associations corroborated the relevance of EFNA5, ZNF521, WWOX, ALG10B, PAM and SDK1 with insomnia, daytime napping, or chronotype traits." (PMID 39070651, 2024).
keratoconus (1 paper, 2020). A degenerative, structural disorder of the eye, characterized by a cone-shaped protrusion of the cornea. "Specifically, we selected seven keratoconus-susceptibility genes (CDH13, SMAD3, ADAM12, CSMD1, NRXN1, CPLX2, and WWOX) for further analysis." (PMID 32737415, 2020).
low grade glioma (1 paper, 2025). A grade I or grade II glioma arising from the central nervous system. "Other relevant pathways in cancer, such as focal adhesion, cytoskeleton regulation, and chemokine signalling (VCL, THBS1-4, FLNA, LAMA2/4/5, HSPG2), might also be influenced indirectly by changes in the WWOX/HIF1A ratio, potentially impacting the overall prognosis of low-grade glioma patients." (PMID 41007296, 2025).
Lymphatic Metastasis (1 paper, 2017). Transfer of a neoplasm from its primary site to lymph nodes or to distant parts of the body by way of the lymphatic system. "The expression of CD133, E-cadherin and WWOX was significantly correlated with lymphatic metastasis, hepatic metastases and UICC stage (p<0.05)." (PMID 28523049, 2017).
mastocytoma (1 paper, 2020). A localized tumor composed of sheets of mast cells without atypia. "Concordant with our data generated in primary MCT tissues, RT-qPCR confirmed that WWOX expression is substantially decreased in canine mastocytoma cell lines when compared with normal canine BMCMCs." (PMID 33129329, 2020). "The basal levels of WWOX remained unchanged despite variation in culture conditions in both canine mastocytoma cell lines evaluated." (PMID 33129329, 2020).
mucinous carcinoma (1 paper, 2005). "The high rate of absence of WWOX protein expression among the mucinous carcinoma group was statistically different compared to the other three histotypes (p = 0.0131)." (PMID 15982416, 2005). "Within the mucinous carcinoma group, we observed that most tumors (7 out of 10 cases) did not stain for WWOX expression." (PMID 15982416, 2005).
myeloproliferative disorder (1 paper, 2019). A clonal hematopoietic stem cell disorder, characterized by proliferation in the bone marrow of one or more of the myeloid (i.e., granulocytic, erythroid, megakaryocytic, and mast cell) lineages. "Although this is an interesting possibility, there remain unanswered questions concerning the role of WWOX and Atg4b in the pathogenesis of the onset of myeloproliferative disorders." (PMID 31699801, 2019).
osteoarthritis (1 paper, 2008). A noninflammatory degenerative joint disease occurring chiefly in older persons, characterized by degeneration of the articular cartilage, hypertrophy of bone at the margins and changes in the synovial membrane. "In addition we detected novel proteins that were deregulated in osteoarthritis, such as SOX11, FGF23, KLF6, WWOX and GDF15." (PMID 19011694, 2008). "Proteins such as SOX11, FGF23, KLF6, WWOX and GDF15 not implicated previously in the genesis of osteoarthritis were identified." (PMID 19011694, 2008).
preeclampsia (1 paper, 2015). Preeclampsia is a hypertensive disorder of pregnancy that is characterized by new-onset hypertension with proteinuria presenting after 20 weeks of gestation, and depending on mild or severe forms may initially present with severe headache, visual disturbances, and hyperreflexia. "These included WWOX (common to preeclampsia, HARs and EPS), a gene that play a role in apoptosis and act as tumor suppressor." (PMID 26641094, 2015).
psoriasis (1 paper, 2023). An autoimmune condition characterized by red, well-delineated plaques with silvery scales that are usually on the extensor surfaces and scalp. "However, our study is predominantly centered on the NF-kB signaling pathway and its modulation by WWOX, potentially overlooking other critical pathways implicated in the pathogenesis of psoriasis." (PMID 38203337, 2023). "In this study, we investigated the correlation of WWOX with poly(I:C)-induced NF-kB signaling pathway in epidermal keratinocytes, which is thought to be critical to the pathogenesis of psoriasis." (PMID 38203337, 2023). "Our research showed increased expression of WWOX in the epidermis of psoriasis patients and the IMQ-treated mouse model." (PMID 38203337, 2023). "In summary, we demonstrated that WWOX was increased in the epidermis of psoriasis and that WWOX knockdown reduced levels of proinflammatory cytokines, the NF-kB marker p-P65." (PMID 38203337, 2023). "We hypothesized that WWOX could be involved in keratinocytes and their inflammatory responses, which play an essential role in the pathogenesis of psoriasis." (PMID 38203337, 2023). "A better understanding of the effect of WWOX associated with PKC signaling on psoriasis might provide novel insights into the mechanisms underlying the development of psoriasis." (PMID 38203337, 2023). "WWOX expression was upregulated in both human psoriatic lesions and the IMQ-induced mouse psoriasis model." (PMID 38203337, 2023). "Additionally, we analyzed public data on WWOX expression in lesional and non-lesional skin biopsies of psoriasis using Gene Expression Omnibus (GEO) profiles provided by NCBI." (PMID 38203337, 2023).
pulmonary arterial hypertension (1 paper, 2020). Pulmonary arterial hypertension (PAH) is a group of diseases characterized by mean pulmonary artery pressure >20 mmHg and elevated pulmonary arterial resistance leading to right heart failure. "A study reported that the loss of WWOX promoted cell proliferation in pulmonary artery smooth muscle cells and contributed to pulmonary vascular remodeling in pulmonary arterial hypertension." (PMID 33308225, 2020).
sarcoma (1 paper, 2025). A usually aggressive malignant neoplasm of the soft tissue or bone. "This underscores the tumor-type specificity of WWOX function, indicating that therapeutic strategies targeting WWOX may be less relevant in sarcomas compared to epithelial cancers." (PMID 41141138, 2025).
serous carcinomas (1 paper, 2005). "It is worth noting that in all instances, normal and tumor, WWOX staining was exclusively cytoplasmic and in some serous carcinomas staining was also localized to the apical cell membrane or luminal border." (PMID 15982416, 2005).